CDT1 (chromatin licensing and DNA replication factor 1)
Diseases named in the same sentence as CDT1 in open-access papers (continued):
Sharing a sentence is not in itself a finding about the gene and the disease.
colorectal cancer (3 papers, 2015 to 2021). A primary or metastatic malignant neoplasm that affects the colon or rectum. "We examined whether DNA re-replication induced by abnormal activation of CDT1 is regulated by histone modification in human colorectal cancer HCT116 cells that contain a pseudo-diploid genome." (PMID 27744293, 2016).
lymphoblastic lymphoma (3 papers, 2012 to 2022). A lymphoma composed of immature small to medium-sized precursor lymphoid cells (lymphoblasts).
osteosarcoma (3 papers, 2020 to 2024). A usually aggressive malignant bone-forming mesenchymal neoplasm, predominantly affecting adolescents and young adults. "This causes the deubiquitination of additional replication factors such as CDT1, facilitating constitutive replication fork movement and supporting osteosarcoma cell proliferation." (PMID 37118828, 2023).
gastric cancer (2 papers, 2021). A primary or metastatic malignant neoplasm involving the stomach. "In human gastric cancer tissues, the mRNA and protein expression levels of NKX6.3 and RPA1 were significantly reduced, whereas CDT1 were markedly increased." (PMID 34893582, 2021). "Additionally, the expression of NKX6.3 shows a strong inverse correlation with CDT1 and a strong positive correlation with RPA1 in tumors derived from mice implanted with HFE-145shNKX6.3#1 and HFE-145shNKX6.3#2 cells and human gastric cancer tissues." (PMID 34893582, 2021).
lung adenocarcinoma (2 papers, 2022 to 2023). A carcinoma that arises from the lung and is characterized by the presence of malignant glandular epithelial cells. "We further investigated the differentially expressed genes (DEGs) related to CDT1 in the immune response of lung adenocarcinoma (LUAD)." (PMID 37790630, 2023).
lymphoma (2 papers, 2021 to 2024). A malignant (clonal) proliferation of B- lymphocytes or T- lymphocytes which involves the lymph nodes, bone marrow and/or extranodal sites. "In various tumors, including breast, lung, and lymphoma, high expression of CDT1 is associated with increased malignancy and decreased survival rates." (PMID 38589907, 2024).
non-small cell lung carcinoma (2 papers, 2012 to 2021). A group of at least three distinct histological types of lung cancer, including non-small cell squamous cell carcinoma, adenocarcinoma, and large cell carcinoma. "Cdt1 expression is increased in colon and non-small-cell lung carcinomas." (PMID 22479651, 2012).
pancreatic cancer (2 papers, 2012 to 2016). "In pancreatic cancer cells, MLN4924 caused accumulation of CDT1, WEE1, and NOXA, in parallel with an enhancement of radiation-induced DNA damage, aneuploidy, G2 arrest and apoptosis." (PMID 27224919, 2016). "Most recently, we found that MLN4924 could act as a novel radiosensitizing agent by causing accumulation of CDT1 and WEE1 to enhance radiation-induced DNA damage, aneuploidy, G2/M arrest and apoptosis in pancreatic cancer cells." (PMID 22457814, 2012). "Unlike what were observed in pancreatic cancer cells, the MLN4924-radiation combination did not further increase the levels of CDT1 and WEE1, but did caused a further increase of p21 in both SK-BR-3 and MCF7 cells." (PMID 22457814, 2012).
breast adenocarcinoma (1 paper, 2022). "Low nucleosome occupancy that corresponds to large nucleosome-free regions were detected at TSSs of CDT1, CRLS1, and SNX13 in chronic myelogenous leukemia cells, and at TSSs of POC1A, and CRLS1in breast adenocarcinoma cells." (PMID 36338962, 2022).
breast invasive carcinoma (1 paper, 2021). "CDT1 expression was significantly higher in tumor tissues than in normal tissues for multiple cancers, including breast invasive carcinoma and stomach adenocarcinoma." (PMID 34631549, 2021).
ciliopathy (1 paper, 2021). A genetic disorder of the cellular cilia or the cilia anchoring structures, the basal bodies, or of ciliary function. "An intriguing connection between MGS and ciliopathy is based on the observation that depletion of ORC1, ORC4, ORC6, CDT1 and CDC6 leads to reduced primary cilia formation." (PMID 33477564, 2021). "When fibroblasts were depleted for ORC1, ORC4, ORC6, CDT1 and CDC6, primary cilia formation was impaired, suggesting that MGS symptoms might constitute a ciliopathy." (PMID 33477564, 2021).
dengue fever (1 paper, 2022). "IFI27, TPX2, CDT1 and CDCA3 are particularly known for their role in cancer, and TPX2 also for its role in the context of infectious diseases, in particular dengue fever." (PMID 35220956, 2022).
dysplasia (1 paper, 2008). A usually neoplastic transformation of the cell, associated with altered architectural tissue patterns. "The nonparametric receiver operating characteristic analysis suggested that MCM2 and CDC45 had a higher accuracy than CDC6 and CDT1 for distinguishing dysplasia from tongue SCC." (PMID 19116018, 2008).
epithelial dysplasia (1 paper, 2008). "CDT1 mRNA expression levels were significantly higher in severe epithelial dysplasia than in mild epithelial dysplasia (p = 0.006), moderate epithelial dysplasia (p = 0.034), and SCC (p = 0.019)." (PMID 19116018, 2008). "There was statistically significant overall difference in CDT1 expression among the different epithelial dysplasia groups and SCC of the tongue (p = 0.034; Kruskal-Wallis test)." (PMID 19116018, 2008). "The mRNA levels of CDC6, CDT1, MCM2 and CDC45 in 31 cases of precancerous epithelial dysplasia and 33 cases of squamous cell carcinoma of the tongue from formalin-fixed, paraffin-embedded specimens were measured using QRT-PCR." (PMID 19116018, 2008). "In this study, we found that CDC6, CDT1, MCM2 and CDC45 mRNA expression analyzed by quantitative real-time PCR are significantly higher in malignant SCC than mild precancerous epithelial dysplasia, and the expression levels in general increase with increasing grade of dysplasia." (PMID 19116018, 2008).
HCMV infection (1 paper, 2012). "Except for a decrease in Cdt1 and an increase in Cdc6, HCMV infection of quiescent fibroblasts results in little change in the levels of expression of pre-RC proteins." (PMID 22586460, 2012). "It is interesting to note that at IE/early times of HCMV infection these factors are differentially regulated: Cdt1 is downregulated whereas Cdc6 is upregulated." (PMID 22586460, 2012). "Alternatively, given that steady state levels of Cdt1 are reduced during HCMV infection, IE86 may sequester Cdt1 to prevent functions of Cdt1 which are perhaps detrimental to viral replication." (PMID 22586460, 2012). "Similarly, analysis of loading of pre-RCs onto cellular DNA also showed that HCMV infection had little effect on chromatin loading of Cdt1 and the ORCs." (PMID 22586460, 2012).
head and neck squamous cell carcinoma (1 paper, 2022). A squamous cell carcinoma that arises from any of the following anatomic sites: lip and oral cavity, nasal cavity, paranasal sinuses, pharynx, larynx, and salivary glands. "Intriguingly, stability or activation of CDT1 or acute depletion of CDT2 could result in re-replication, which radio-sensitizes head and neck squamous cell carcinoma (HNSCC) cells." (PMID 35173548, 2022).
ischemic heart disease (1 paper, 2022). "Among the genes, 1-hop and 2-hop neighbors in the underlying network, were chromatin licensing and DNA replication factor 1 (CDT1), minichromosome maintenance complex component 5 (MCM5), and cAMP-responsive element-binding protein 1 (CREB1), which have been linked to ischemic heart disease before." (PMID 35903362, 2022).
kidney cancer (1 paper, 2024). Primary or metastatic malignant neoplasm involving the kidney. "CDC6 and CDT1, which act as risk factors for patients’ prognosis, showed a low enough gDS in all kidney cancer cells to show that their deletion severely influences cells’ viability." (PMID 38728235, 2024). "CDC6 and CDT1, especially, represented the lowest gDS in kidney cancer cells, indicating that deletion of these two genes severely affects tumour cell viability." (PMID 38728235, 2024). "Therefore, it is considered that CDC6 and CDT1 promote kidney cancer by regulating these oncogenic pathways." (PMID 38728235, 2024).
lymph node metastasis (1 paper, 2024). "The results showed that CDC45 and CDT1 were highly expressed in the lymph node metastasis group, while ALDH1A1 and ASAH1 were downregulated." (PMID 38589907, 2024).
microtia (1 paper, 2024). "In the non-syndromic microtia group, the most frequently found gene was GSC exon 2 (25%; 6) and FANCB (16.67%); HOXA2, GSC exon 3, MARS1, CDT1 were found respectively in two (8.33%) cases." (PMID 38594752, 2024). "As reported in this review, the major gene disorder related to microtia phenotype is found in TCOF1 (32.82%; 28 cases), followed by GSC exon 2 (6.82%), FANCB (4.55%), SIX2 (3.41%), HSPA9 (3.41%) and CDT1 (3.41%) with each characteristic." (PMID 38594752, 2024). "We found 88 cases of genetic data related to microtia, including TCOF1 (31.82%), GSC exon 2 (6.82%), FANCB (4.55%), SIX2 (3.41%), HSPA9 (3.41%), and CDT1 (3.41%)." (PMID 38594752, 2024). "However, the association between them is still unclear because there is still a lack of studies on non-syndromic microtia and CDT1 genes." (PMID 38594752, 2024). "In the syndromic microtia group, the most common genes were TCOF1 (43.75%), SIX2 (4.69%), and HSPA9 (4.69%), while in the non-syndromic microtia group, the most frequently found gene was GSC exon 2 (25%), FANCB (16.67%), HOXA2 (8.33%), GSC exon 3 (8.33%), MARS1 (8.33%), and CDT1 (8.33%)." (PMID 38594752, 2024). "Based on our findings, 64 cases (72.72%) were syndromic microtia [TCOF1 (43.75%), SIX2 (4.69%), and HSPA9 (4.69%)] and 24 cases (27.27%) were non-syndromic microtia [GSC exon 2 (25%), FANCB (16.67%), HOXA2 (8.33%), GSC exon 3 (8.33%), MARS1 (8.33%), CDT1 (8.33%)]." (PMID 38594752, 2024).
neuroblastoma (1 paper, 2021). Neuroblastoma (NB) is the most common solid, extracranial childhood tumor.
progeroid syndrome (1 paper, 2016). A group of rare genetic disorders which mimic physiological aging, making affected individuals appear to be older than they are. "Therefore, we examined the effects of IR and UV irradiation on Cdt1-switching and SA-β-gal-positive cells as well as the duration of G2 checkpoint activation in fibroblasts containing Fucci indicators from patients with various progeroid syndromes." (PMID 27507734, 2016).
prostate tumor (1 paper, 2024). "Interestingly, ESM1 and CDT1 have been previously associated with prostate tumor progression." (PMID 38597610, 2024).
SCC of the tongue (1 paper, 2008). "In other words, MCM2 and CDC45 had a higher accuracy than CDC6 and CDT1 for distinguishing precancerous stages from malignant tongue SCC." (PMID 19116018, 2008). "Therefore, overexpression of CDC6 and CDT1 in SCC of the tongue may be due, at least in part, to an E2F-1 to -3 mediated effect." (PMID 19116018, 2008). "The area under the ROC curve (AUC) was 0.679 for CDC6 (p = 0.032), 0.808 for CDT1 (p = 0.000), 0.933 for MCM2 (p = 0.000) and 0.836 for CDC45 (p = 0.000), indicating that MCM2 and CDC45 were superior to CDC6 and CDT1, and could be used as useful tumor markers in diagnosing tongue SCC." (PMID 19116018, 2008).
small cell lung carcinoma (1 paper, 2007). Small cell lung cancer (SCLC) is a highly aggressive malignant neoplasm, accounting for 10-15% of lung cancer cases, characterized byrapid growth, and early metastasis. "This is consistent with the observation that Cdt1 and Cdc6 levels are upregulated in small cell lung carcinomas and that Cdt1 overexpression could cause chromosome damage in fibroblasts." (PMID 17319958, 2007).
Stroke (1 paper, 2012). Sudden impairment of blood flow to a part of the brain due to occlusion or rupture of an artery to the brain. "The stress response following stroke induced several replication-associated genes such as CDT1 and E2F3." (PMID 23284893, 2012).
virus infection (1 paper, 2012). "In contrast, removal of Cdt1 during the course of a virus infection had profound effects on viral DNA replication." (PMID 22586460, 2012).
cancer (65 papers, 2006 to 2025). A tumor composed of atypical neoplastic, often pleomorphic cells that invade other tissues. "Consistent with this, the downregulation of geminin, an inhibitor of CDT1, has been shown to cause re-replication-induced DNA damage and apoptosis in cancer cells." (PMID 38336851, 2024). "Chromatin licensing and DNA replication factor 1 (CDT1), a key regulator of cell cycle control and replication in eukaryotic cells, has been implicated in various cancer-related processes." (PMID 37790630, 2023). "Aberrant expression of CDT1 causes DNA re-replication, activation of the damage response and apoptosis in human cancer cells." (PMID 35548337, 2022). "Overexpression of CDT1 is connected with irregular cell replication, activation of DNA damage checkpoints, and predisposition to malignant transformation in various human cancers." (PMID 35884419, 2022). "Cdt1 transcription is driven by the E2F family of transcription factors (see Section 4.1), and one of the most frequently-mutated regulatory pathways in cancers is the Rb-E2F pathway." (PMID 28025526, 2016). "We suggest that deregulation of DNA replication via Aurora-A–geminin–CDT1 axis can be used as a potential diagnostic and therapeutic target in cancer." (PMID 26380219, 2015). "Aberrant expression of CUL4 can be linked to unstable turnover of Cdt1 leading to DNA replication defects, aneuploidy and genomic instability and even cancer." (PMID 26460955, 2015). "Previous studies have found CRL4CDT2 targets many substrates for destruction associated with cancer that include CDT1, p21 and CHK1." (PMID 26460955, 2015). "It is worth noting that although several mechanisms regulate CDT1 degradation, all cancer cell lines shown here were similarly susceptible to CDT2 loss, though they are characterized by different pattern of mutations." (PMID 25115388, 2014). "Furthermore, it has been demonstrated that drugs like MLN4924, which stabilizes CDT1, can induce re-replication, resulting in cell death in checkpoint-deficient cancer cells." (PMID 38336851, 2024). "This cancer cell sensitivity to Gmnn loss may involve greater relative ability of non-cancer cell lines to use alternate molecular mechanisms to control Cdt1 activity by proteolysis, and/or relative over-expression of Cdt1 and pre-RC proteins in many cancer cell contexts." (PMID 29234490, 2017). "One such compound, AF615, blocks cell cycle progression and reduces cell survival in various cancer cell lines by mimicking the cellular effects of abnormal CDT1/Geminin expression." (PMID 40433415, 2025). "The overexpression of CDT1 in various cancers, including HCC, induces abnormal replication and malignant transformation." (PMID 40433415, 2025). "This compound selectively affects cancer cells with minimal impact on normal cells, highlighting its potential for cancer treatment targeting CDT1." (PMID 40433415, 2025). "Knowing CDT1 function is essential for us to better understand cancer transformation and progression." (PMID 37790630, 2023). "Given its significant role in cancer, the focus on CDT1 in this study is justified as it holds promise as a potential biomarker or therapeutic target for cancer treatment." (PMID 37790630, 2023). "The cancer associated biological function of some were known little about, such as CBX2, CBX5, CDT1, TOPBP1 and RUNX2, but whose implication in cancer worth further exploration based on emerging evidences." (PMID 37917664, 2023). "Numerous studies have shown that CDT1 is overexpressed in a variety of cancers, and this overexpression leads to low survival rates." (PMID 37790630, 2023). "Cdt1 transcription is controlled by the Rb-E2F pathway, which is frequently deregulated in cancers to drive the aberrant overexpression of E2F target genes." (PMID 37760529, 2023).